BMI1 (BMI1 proto-oncogene, polycomb ring finger)
Diseases named in the same sentence as BMI1 in open-access papers (continued):
Sharing a sentence is not in itself a finding about the gene and the disease.
epithelial ovarian tumor (1 paper, 2010). "In summary, in this study, we describe, for the first time, protein expression and amplification patterns of Bmi-1 in normal human ovary, benign, borderline and malignant epithelial ovarian tumor tissues." (PMID 20377880, 2010).
Fanconi anemia (1 paper, 2020). Fanconi anemia (FA) is a hereditary DNA repair disorder characterized by progressive pancytopenia with bone marrow failure, variable congenital malformations and predisposition to develop hematological or solid tumors. "Lastly, BMI1 knockout mice display significant defects in the hematopoietic system and bone marrow development, a phenotype reminiscent of the Fanconi Anemia pathway deficiency." (PMID 32142505, 2020). "Based on these data, we provide a model that BMI1 or RNF2 deficiency causes R-loop formation and TRCs at CFSs, which can be counteracted by the Fanconi Anemia proteins." (PMID 32142505, 2020).
Fibroadenoma (1 paper, 2010). A benign tumor of the breast characterized by the presence of stromal and epithelial elements. "When we compared the transcription level of Bmi-1 and Mel-18 in all categories (NC, non cancer controls, F, fibroadenomas N, normal and T tumor) we observed an inverse relationship between the transcription level of the two genes." (PMID 21162745, 2010). "The transcription level of Bmi-1 and Mel-18 in all clinical categories (non cancer controls, fibroadenomas, normal, and tumor) was inversely correlated." (PMID 21162745, 2010).
frontotemporal dementia (1 paper, 2020). Frontotemporal dementia (FTD) comprises a group of neurodegenerative disorders, characterized by progressive changes in behavior, executive dysfunction and language impairment, as a result of degeneration of the medial prefrontal and frontoinsular cortices. "Not only is BMI1 expression reduced significantly in some aging tissues and senescent cells, but further reduction in the case of LOAD is unique, compared with other neurodegenerative disorders such as EOAD, frontotemporal dementia and Lewy body dementia." (PMID 32708145, 2020).
glaucoma (1 paper, 2017). Increased pressure in the eyeball due to obstruction of the outflow of aqueous humor. "Moreover, our findings indicate that suppression of the TBK1/Akt Ser473/Bmi1 Ser316/p16 axis is a potential therapeutic strategy for minimizing RGC senescence in retinal ischemia and glaucoma." (PMID 28425986, 2017).
heart failure (1 paper, 2023). Inability of the heart to pump blood at an adequate rate to meet tissue metabolic requirements. "Hub genes including LRRK2, BMI1, KBTBD7, and FFAR2 were associated with the risk of heart failure." (PMID 38137330, 2023).
Hypoglycemia (1 paper, 2022). A decreased concentration of glucose in the blood. "Changes in BMI-1 expression are correlated with changes in AKT phosphorylation but decreased expression of BMI-1 during prolonged insulin stimulation is accompanied by increased expression in PTEN only in hypoglycemia conditions." (PMID 36497428, 2022).
hypogonadism (1 paper, 2021). A disorder characterized by decreased function of the gonads. "Our study uncovered a novel epigenetic mechanism in steroidogenesis involving BMI1-mediated gene silencing and provides potential therapeutic targets for the treatment of hypogonadism." (PMID 33928089, 2021).
infectious mononucleosis (1 paper, 2019). A condition characterized by an increase in mononuclear white blood cells and swollen lymph nodes, which is usually caused by infection with the Epstein-Barr virus. "ChIP-seq was performed to study the localization of BMI1 and SUZ12 across the host genome in an LCL produced by infection of 1o B cells with a recombinant EBV of B95.8 background (prototypical transforming EBV, originally derived from an infectious mononucleosis patient)." (PMID 30649516, 2019).
intervertebral disc degeneration (1 paper, 2020). "Taken together, from the data in the current study, a model illustrating the possible mechanism of Bmi‐1 regulating oxidative stress response upon intervertebral disc degeneration can be proposed." (PMID 32583517, 2020). "In this work, we explored the role of Bmi‐1 on mouse intervertebral disc degeneration using Bmi‐1 gene knockout mice in vivo and organ culture in vitro and investigated the effect of N‐acetylcysteine (NAC) treatment on intervertebral disc degeneration." (PMID 32583517, 2020).
intrahepatic cholangiocarcinoma (1 paper, 2022). A carcinoma that arises from the intrahepatic bile duct epithelium in any site of the intrahepatic biliary tree. "Downregulation of SALL4 contributed to a decrease in B-cell-specific Moloney murine leukemia virus integration site 1 (Bmi-1) expression and inactivated the Wnt3a/β-catenin signaling pathway in intrahepatic cholangiocarcinoma (ICC)." (PMID 35216168, 2022).
invasive ductal adenocarcinomas (1 paper, 2014). "In this study we show that Bmi1 upregulation is associated with grade III invasive ductal adenocarcinomas of Indian patients, further supporting its role as a prognostic marker." (PMID 25348805, 2014).
lung adenoma (1 paper, 2009). A benign, well circumscribed epithelial neoplasm that arises from the bronchus or the lung parenchyma. "Analysis of lung adenoma cells in the absence or presence of Bmi1 did not reveal differences at the morphological and at cell marker expression level." (PMID 19156217, 2009).
lymphatic disease (1 paper, 2011). "In the future, the combination of molecular markers with proven predictive value for lymphatic disease like ECAD, podoplanin, p16, bmi-1, LOX and histopathological features could allow an individual risk stratification with possible impact on treatment strategy." (PMID 21639893, 2011).
mature T cell lymphoma (1 paper, 2017). "High expression of MALAT1 as well as BMI1 was related to poor prognosis in patients with mature T cell lymphoma." (PMID 28412742, 2017).
Merkel cell carcinoma (1 paper, 2013). "Our research group could show as well that Bmi-1, a stem cell marker, was homogenously and highly positive in all Merkel cell carcinoma samples." (PMID 23691324, 2013). "Recently, we conducted a study looking at a distinct panel of target proteins and we could find that therapeutically useful targets c-kit, Bmi-1, Mcl-1, VEGF-A and VEGF-C, VEGF-R2, PDGF-α and PDGF-β were expressed in Merkel cell carcinoma." (PMID 23691324, 2013).
mesothelioma (1 paper, 2010). A usually malignant and aggressive neoplasm of the mesothelium which is often associated with exposure to asbestos. "The cells expressed mesothelioma markers together with some typical genes involved in stemness such as BMI-1 and CD90." (PMID 20175889, 2010). "By real time PCR we found that our cell cultures expressed high mRNA levels of typical mesothelioma markers as mesothelin (MSLN) and calretinin (CALB2), of BMI-1, a stemness marker and of DKK1, a potent Wingless [WNT] inhibitor." (PMID 20175889, 2010). "By real time PCR we found that our cell lines expressed high mRNA levels of typical mesothelioma markers as mesothelin (MSLN) and calretinin (CALB2), and of BMI-1, a stemness marker, and DKK1, a potent Wingless [WNT] inhibitor." (PMID 20175889, 2010).
metastatic cancers (1 paper, 2019). A carcinoma which has spread from the original site of growth to another anatomic site. "As the well‐known vital transcription factors, Twist and Bmi1 play an important role in metastasis and their dysregulation has been demonstrated in metastatic cancers." (PMID 30353649, 2019).
mucositis (1 paper, 2018). Mucositis is inflammation and damage of the mucous membranes lining the mouth and other parts of the gastrointestinal (GI) tract. "In a rat model of radiotherapy‐induced mucositis, Bmi1 upregulation was observed 8 days after irradiation." (PMID 29479858, 2018). "In the rat model of radiotherapy‐induced mucositis, Bmi1 was upregulated after DNA damage occurred." (PMID 29479858, 2018).
myxoma (1 paper, 2020). A benign soft tissue neoplasm characterized by the presence of spindle and stellate cells, lobulated growth pattern, and myxoid stroma formation. "Also, these clonogenic c-kitpos/CD45neg/CD31neg myxoma-derived CSCs express OCT-4, NANOG, BMI-1, NKX2.5, and ISL-1 and form cardiospheres at a rate similar to normal human CSCs even though serial spherogenesis was reduced." (PMID 32330934, 2020).
oligospermia (1 paper, 2023). Decreased number of spermatozoa in the semen. "In a previous study, male mice with BMI1 deficiency were found to exhibit severe oligospermia and significantly reduced testicular volume, thus suggesting that BMI1 is necessary for maintaining normal reproductive function." (PMID 37139440, 2023).
oropharyngeal carcinoma (1 paper, 2017). Carcinoma, predominantly squamous cell, arising from the epithelial cells of the oropharynx. "This is further supported by a study reporting that BMI1 protein expression was lost in less than half of the 40 p16 positive oropharyngeal carcinoma oral tumors tested." (PMID 29069809, 2017).
oropharyngeal squamous cell carcinoma (1 paper, 2023). "In another study, HPV-positive human oropharyngeal squamous cell carcinoma specimens showed lower Bmi-1 expression than HPV-negative tumors (n = 202)." (PMID 36726797, 2023).
oropharyngeal tumors (1 paper, 2017). "Thus, a loss of BMI1 expression appears unrelated to increased p16 transcription, at least in the context of oropharyngeal tumors." (PMID 29069809, 2017).
ovarian failure (1 paper, 2021). "A strong ovary-protecting effect of NAC has been demonstrated in the contexts of ionizing radiation-induced ovarian failure, ovarian torsion, ovarian grafts, and in Bmi1-knockout female mice." (PMID 34367464, 2021).
pancreatic IPMN (1 paper, 2014). "Additionally, we examined the expression of BMI-1 (B lymphoma Moloney murine leukemia virus insertion region 1 homolog), another polycomb protein, during pancreatic IPMN progression, since BMI-1 plays an important role in cancer cell proliferation via transcriptional repression." (PMID 25084021, 2014). "To further assess the underlying molecular mechanism of the downregulation of p27Kip1 during pancreatic IPMN progression, we focused on the alteration of EZH2 and BMI-1, which function as transcriptional repressors during tumorigenesis." (PMID 25084021, 2014).
Pancytopenia (1 paper, 2022). An abnormal reduction in numbers of all blood cell types (red blood cells, white blood cells, and platelets). "Bmi1 is critical for maintenance of HSC self-renewal capacity via suppressing p16Ink4a and p19Arf signaling 30, which supported by the evidence that Bmi1 KO mice develop serious pancytopenia with dramatic reduction of HSCs in BM." (PMID 35342358, 2022).
pituitary adenomas (1 paper, 2012). "Together, our results show that transgenic over expression of Bmi1 is sufficient to generate adrenocorticotropic pituitary tumors and a subset of clinical specimens of pituitary adenomas show high expression of Bmi1." (PMID 22574128, 2012). "Human pituitary adenomas show Bmi1 overexpression in over 50% of the cases, which indicates that Bmi1 could be causally involved in formation of these tumors similarly as in our mouse model." (PMID 22574128, 2012). "To analyze whether BMI1 is over expressed in human pituitary adenomas, we performed immunohistochemistry." (PMID 22574128, 2012).
prediabetes (1 paper, 2025). "miR-27 was up-regulated in obese prediabetes, targeting regulators of oxidative stress and apoptosis such as BCL2, BMI1, FOXO3, and suppressing SIRT1, thereby amplifying IL-6 production." (PMID 41400625, 2025).
progressive ataxia (1 paper, 2015). "Bmi1-knockout mice exhibit epileptic-like seizures and progressive ataxia." (PMID 26696825, 2015).
retinal detachment (1 paper, 2025). An eye emergency condition which may lead to blindness if left untreated. "Subretinal (SR) delivery is known to suppress ERG amplitudes in mice due to retinal detachment during injection; thus, functional analysis was not performed in AAV5.BMI1-treated animals." (PMID 40565365, 2025).
retinal ischemia (1 paper, 2017). A ischemic disease that involves the retina. "We found that acute IOP elevation-induced retinal ischemia directly increases TBK1 expression, triggering Akt S473 phosphorylation, activating Bmi1 phosphorylation, and upregulating the expression of p16, which leads to RGC senescence in cell culture and an IOP-induced retinal ischemia mouse model." (PMID 28425986, 2017).
rheumatoid arthritis (1 paper, 2021). A chronic, systemic autoimmune disorder characterized by inflammation in the synovial membranes and articular surfaces. "The overexpression of both Dkk1 and Bmi1 was found to be related to cytokine‐cytokine receptor interactions, rheumatoid arthritis, renin secretion, and nitrogen metabolism in our study." (PMID 33639034, 2021).
serous carcinomas (1 paper, 2010). "In serous carcinomas, intensive expression of Bmi-1 was more likely to be observed in grade 2/3 tumors than that in grade 1 tumors." (PMID 20377880, 2010).
serous ovarian cancer (1 paper, 2017). "The identified CK2α-BMI1 liaison is of clinical significance as high CK2α expression strongly correlates with the elevated BMI1 protein levels in high grade serous ovarian cancer tissues." (PMID 28270146, 2017). "Clinically, compared to normal fallopian tube epithelial tissues, the expression of both BMI1 and CK2α were significantly higher in tumor tissues obtained from high-grade serous ovarian cancer patients." (PMID 28270146, 2017). "Correlations between expression of CK2α and BMI1 were determined from cell lines and formalin fixed paraffin embedded tissues representing the normal fallopian tube epithelium and high grade serous ovarian cancer samples." (PMID 28270146, 2017).
serous ovarian tumors (1 paper, 2017). "Therefore, we analyzed BMI1 and CK2α levels in a panel of twenty high-grade serous ovarian tumors and two normal fallopian tube epithelial (FTE) tissues by immunoblotting." (PMID 28270146, 2017).
skin changes (1 paper, 2025). "To gain further insights into its involvement in skin aging processes, we examined the onset and severity of age-related skin changes in Bmi-1-deficient mice using histological analysis with H&E staining which revealed a reduction in epidermal thickness and pilosebaceous unit count." (PMID 40153371, 2025).
soft tissue neoplasm (1 paper, 2016). A benign, intermediate, or malignant neoplasm that arises from the soft tissue. "ES are bone or soft tissue neoplasms with a prominent immature stemness phenotype maintained by epigenetic repressors BMI1 and EZH2." (PMID 27363011, 2016).
squamous lung cell carcinoma (1 paper, 2021). "EZH2 and BMI1 are similarly involved in lung tumour development, with EZH2 found highly expressed in squamous lung cell carcinoma together with BMI1 and the cellular proliferation marker Ki67." (PMID 33804165, 2021).
status epilepticus (1 paper, 2015). Status epilepticus is defined as a continuous seizure lasting more than 30 min, or two or more seizures without full recovery of consciousness between any of them. "Here, we explored the transcriptional response of genes associated with polycomb repressive complex (PRC) 1 (Ring1A, Ring1B, and Bmi1) and PRC2 (Ezh1, Ezh2, and Suz12), as well as additional transcriptional regulators Sirt1, Yy1, and Yy2, in a mouse model of status epilepticus (SE)." (PMID 25806020, 2015).
thyroid tumor (1 paper, 2021). A benign or malignant neoplasm affecting the thyroid gland. "Nevertheless, these observations collectively suggested that the Shh pathway promotes SOX2 and BMI1 expression in thyroid tumor cell lines." (PMID 33499351, 2021).
tongue tumors (1 paper, 2016). "We found that Bmi1+ cells produced clusters of single-colored cells in developing tumors, suggesting that Bmi1+ tumorigenic cells behaved as cancer stem cells and continually provided transit-amplifying cells in tongue tumors, contributing to tumor growth." (PMID 28004815, 2016). "The number of Bmi1-positive cells that remained as single cells gradually decreased in the tongue tumors, suggesting that Bmi1 was also expressed in differentiated cells, which could neither self-renew nor supply tumor cells; the cells underwent terminal differentiation and finally disappeared." (PMID 28004815, 2016). "We could not determine which of these two possibilities was applicable to the resting Bmi1+ tumor cells, mainly because the mice with tongue tumors did not survive for a sufficiently long period." (PMID 28004815, 2016).
type II diabetes (1 paper, 2016). "It's deficiency causes depletion of neural, hematopoietic and other adult organ-specific stem cells in the mouse model, and BMI1 knockout mice exhibit segmental features of the accelerated ageing and other pathologies such as type II diabetes." (PMID 27105531, 2016).
uterine carcinosarcoma (1 paper, 2019). A usually aggressive malignant neoplasm arising from the uterine corpus and less often the cervix. "Studies using the CS99 cell line, which is derived from uterine carcinosarcomas, showed that inhibition of BMI1 (BMI1 proto-oncogene, polycomb ring finger) with the BMI1 inhibitor, PTC-028, led to increased apoptosis and decreased cell viability in vitro and delayed tumor growth in vivo." (PMID 31717878, 2019). "Studies have shown that CD133+ cells isolated from uterine carcinosarcomas have properties of cancer stem cells such as differentiation into both epithelial and stromal lineages, chemotherapy resistance, increased expression of stem cell markers including BMI1, and in vivo transplantable tumors." (PMID 31717878, 2019).
xerostomia (1 paper, 2021). Dryness of the mouth resulting from reduced salivary secretion. "This suggested that the increased saliva viscosity and reduced amount of saliva observed in Bmi-1-/- mice are similar to the symptoms of xerostomia." (PMID 33465144, 2021).